CD4 (CD4 molecule)
Diseases named in the same sentence as CD4 in open-access papers (continued):
Sharing a sentence is not in itself a finding about the gene and the disease.
lymphoma (continued). "CD4+ T cells specific for Ig-derived neoantigens were isolated from PB and were found to mediate the killing of autologous lymphoma cells." (PMID 35008305, 2021). "Pre-vaccination PB lymphocytes (PBLs) were cultured either with media or with autologous, irradiated, CpG-ODN-activated lymphoma cells, and the expression of CD4, CD25, and FOXP3 was assessed." (PMID 35008305, 2021). "In both the A20.IIA-GFP and BAL17CNS lymphoma models, CD4+ and CD8+ T cells, reactive B cells, and increased numbers of CD11b+ and CD11c+ cells intermingle with tumor cells." (PMID 34944954, 2021). "In mouse lymphoma and solid tumour models, blockade of PD-1 can enhance CD4+ T cell-mediated anti-tumour immunity and in NSCLC patients, CD4+ immunity was required for clinical responses to PD-1/PDL-1 blockade therapy." (PMID 33597595, 2021). "Along these lines, T cell responses against the EBV latency I antigen, particularly in healthy virus carriers frequent EBNA1-specific CD4+ T cells, seem to be lost prior to EBV-associated lymphoma development in HIV patients." (PMID 34778072, 2021). "In another model of aggressive lymphoma (Eμ-Myc), T cell zone resident stromal cells were shown to selectively retain CD4+ T cells in the TME to support tumor progression via CD40L signaling." (PMID 33842331, 2021). "IL-10 expression did not significantly differ between subtype infection profiles but did show a marked increase—accompanying decreased CD4:CD8b ratio—in a koala with lymphoma and co-infected with KoRV-A and -B, thus suggesting immunosuppression." (PMID 33316950, 2020). "Currently, 3 recruiting clinical phase-I studies are investigating the clinical response, safety, and pharmacokinetics of using CD4-specific CARTs in patients with CD4 + T cell leukemias/lymphomas (NCT04162340, NCT04219319, NCT03829540)." (PMID 33384022, 2020). "Further investigation of a KoRV-B- and C-positive adult koala that died (found to have lymphoma) revealed immunosuppression characterized by a decreased CD4:CD8b ratio and increased IL-10 expression." (PMID 33316950, 2020). "In patients with low CD4 cell count (< 200/μl), the incidence of lymphoma subtypes as immunoblastic DLBCL, PEL, or PBL increases." (PMID 32803474, 2020). "High levels of C5a are related to tumorigenesis accompanied by reduced IFN-γ-producing CD8 and CD4 cells, while a low level of C5a is associated with decreased tumor burden with increased IFN-γ-producing CD4 and CD8 T cells in mice with lymphoma." (PMID 32626741, 2020). "Most lymphomas were CD4 and CD8 double positive, suggesting that transformation occurred at this stage of T lymphocytes development." (PMID 32139898, 2020). "In two of the 3 CD4+ lymphomas (#9 and #10, 66.7%), an aberrant phenotype was found, with 60.8 and 87% of cells, respectively, staining positive for CD4, but mostly negative for CD5." (PMID 32903608, 2020). "Another Ca2+ channel, the transient receptor potential cation channel subfamily V member 2 (TRPV2), showed lower response to membrane stretching when silenced in Jurkat (human lymphoma CD4+ cells)." (PMID 32384769, 2020). "Skewed Tfh cell differentiation in splenic CD4+ T cells prior to lymphoma development has also been reported." (PMID 32704161, 2020). "The cytotoxicity against lymphoma cells (IC50: 1 μM) observed for cd4(Q5K,D9K), a cyclic dimer rich in cationic charge content, indicated the importance of net positive charge in the interaction with cancer cell membranes." (PMID 32153522, 2020). "We showed that a murine lymphoma was able to produce a soluble factor that inhibited the function of dendritic cells in activating the CD4+ T cells." (PMID 31602007, 2019). "In this study, a specific antibody against K-ε-GG was used to isolate ubiquitinated peptides from CD4+ T cells and MD T lymphoma cells." (PMID 31035338, 2019). "In the current study, a monoclonal antibody against a ubiquitinated peptide (K-ε-GG) was used to isolate ubiquitinated peptides of T lymphoma cells and CD4+ T cells." (PMID 31035338, 2019).
lymphoma (continued). "The primary site of MDV latent infection is the activated CD4+ T-lymphocytes in the peripheral blood, resulting in lymphomas in the visceral organs from 3 weeks post-infection." (PMID 31798630, 2019). "The MSB1 lymphoblastoid cell line is an MDV-transformed CD4+ T-cell line derived from a spleen lymphoma induced by the BC-1 strain of MDV-1." (PMID 31798630, 2019). "Overall, the data indicate that CD4+ T cells expressing the B7H6-specific CAR/T-bet (∆TBOX) improved the efficacy of the CAR T cell treatment in the RMA-B7H6 lymphoma model." (PMID 29515240, 2018). "In murine model of lacrimal gland B-cell lymphomas, those lymphoma cells that were coinjected with MSCs were found to have increased CD4+ Foxp3+ regulatory T cells as well as CD11b+ Ly6C+Ly6G– MDSCs." (PMID 30101129, 2018). "In the spontaneous lymphomas, two main distinct subpopulations of tumor cells were observed, namely, CD4+ lymphocyte-origin tumor cells and Oct4+ germ cell-like cells." (PMID 30302273, 2018). "The proportion of CTLA-4+ cells in CD4+ lymphocyte populations obtained from PBMCs was significantly higher in the lymphoma group (1.40% ± 0.92%) than in the control group (0.62% ± 0.26%, P = 0.018)." (PMID 30040869, 2018). "Unexpectedly within the CD4+CXCR5+CCR6+ population there were significant reductions in CCR6 expression in lymphoma patients as compared to normal subjects." (PMID 29293620, 2018). "Two groups have recently reported that, C/EBPβ plays an essential role in limiting proliferation of CD4+ T cells and IFNγ production in the case of lymphoma-educated DCs and Gr1+CD11b MDSC." (PMID 30544623, 2018). "UBR5 protein was dramatically upregulated in all T-cell leukemia/lymphoma cell lines compared to both naïve and memory CD4 T-cells." (PMID 29441057, 2018). "In summary, this study indicates that PD-1 expression is up-regulated on both peripheral and tumor infiltrating T cells and that CTLA-4 expression is up-regulated on CD4+ T cells from peripheral blood obtained from dogs with B cell high grade lymphoma." (PMID 30040869, 2018). "In this study, CTLA-4 expression on peripheral CD4+ and CD8+ lymphocytes and CD4+ lymphocytes obtained from LNCs was found to be associated with poor prognosis in canine B cell high grade lymphomas." (PMID 30040869, 2018). "Human CD4+ lymphoma H9 cells were transfected with the cDNA library and stained with an Allophycocyanin (APC)-conjugated SEMA4A-Fc protein." (PMID 29467366, 2018). "MFIs of PD-1 on the surface of CD4+ lymphocytes obtained from PBMCs and LNCs were significantly higher in the lymphoma group (PBMCs, 1169 ± 573, P = 0.004; LNCs, 2655 ± 1116, P < 0.001) than in the control group (PBMCs, 617 ± 262; LNCs, 933 ± 375)." (PMID 30040869, 2018). "Flow cytometric analysis revealed that the expression of PD-1 on CD4+ peripheral and tumor infiltrating lymphocytes and CTLA-4 on CD4+ peripheral lymphocytes was significantly higher in the lymphoma group than in the control group." (PMID 30040869, 2018). "We found that CTLA-4 expression on CD4+ T cells obtained from PBMCs was significantly higher in the lymphoma group than in the control group." (PMID 30040869, 2018). "In this study, significantly higher expression of PD-1 was observed on CD4+ T cells obtained from LNCs from dogs with lymphoma, and CD8+ T cells tended to up-regulate these molecules." (PMID 30040869, 2018). "EG-7 lymphoma cells were injected subcutaneously into the flanks of wild-type (WT) mice and 17 days later CD4+ and CD8+ tumour-infiltrating lymphocytes (TIL) or T cells residing in the spleen were sorted and analysed for Grail expression by real-time (RT)-PCR." (PMID 28798332, 2017). "PDE4B was reported to be highly expressed in CD4+ lymphoid cancer cells, with a role in promoting angiogenesis in B-cell lymphoma." (PMID 29061142, 2017).
lymphoma (continued). "CD4CAR NK-92 cells specifically and robustly eliminated diverse CD4+ human T-cell leukemia and lymphoma cell lines (KARPAS-299, CCRF-CEM, and HL60) and patient samples ex vivo." (PMID 29348865, 2017). "During 24-hour co-culture experiments, CD4CAR NK-92 cells showed profound killing of CD4+ leukemia/lymphoma cells at the low effector cell to target cell ratio (E:T) of 2:1 and the standard 5:1 ratio." (PMID 29348865, 2017). "Correspondingly, supplementation of exogenous recombinant IL-7 markedly amplified and sustained polyfunctional CD4+ effector cells, resulting in improved therapeutic outcome in a mouse lymphoma model." (PMID 28939858, 2017). "Apart from aGvHD we also studied the GvT effect against the BCL1 lymphoma and performed a series of in vitro experiments to disect the responsiveness of CD4+ and CD8+ T cells toward Hsp90 inhibition." (PMID 27980780, 2016). "Although 84% of our patients were on ART, median ART duration at lymphoma diagnosis was only 9.9 months with median CD4 count 121 cells/μL, highlighting a need for continued scale-up and earlier ART application." (PMID 26934054, 2016). "Tumors from animals with residual lymphoma showed higher numbers of CD4+ and CD8+ and similar numbers of NK, neutrophils and Tregs infiltrating cells as compared with non-treated animals." (PMID 27876058, 2016). "Among HIV-positive patients, ART use, CD4 count, and HIV RNA at lymphoma diagnosis are comparable to contemporary HIV-associated NHL cohorts in the US, as are outcomes for patients treated with CHOP." (PMID 26934054, 2016). "Compared with healthy controls (median, 2.56% of CD4+ T cells; range, 0.66–7.95%; n = 39), the percentage of peripheral Th17 subset was significantly decreased in lymphoma patients (median, 1.88%; range, 0.35–5.59%; n = 48; P = 0.0328)." (PMID 26812681, 2016). "The proportion of CD4+IFN-γ-producing T cells (Th1 subset) was significantly higher in patients with lymphomas (median, 25.3% of CD4+ T cells; range, 5.7–72.1%; n = 48) than that in normal individuals (median, 17.6%; range, 7.9–48.9%; n = 39; P = 0.0030)." (PMID 26812681, 2016). "Median CD4 at lymphoma diagnosis was 121 cells/μL (IQR 61–244), median HIV RNA was 3.5 log10copies/mL (IQR 1.3–4.8), and 43% had suppressed HIV RNA <400 copies/mL." (PMID 26934054, 2016). "This was also observed in human lymphoma/leukemia CD4+ T-cell lines relative to primary CD4+ T-cells that have high endogenous SAMHD1 expression." (PMID 26416562, 2015). "In this study, we show that the severity of inflammation is correlated with the development of lymphomas in HBZ-Tg mice, suggesting that HBZ-mediated inflammation is closely linked to oncogenesis in CD4+ T cells." (PMID 26296091, 2015). "Some authors reported good prognostic value of Foxp3+CD4+ T cells in head and neck cancer, colorectal carcinoma bladder cancer and lymphoma." (PMID 26604855, 2015). "Lymphomas that developed in irradiated recipient mice were mostly CD4+CD8+ and were positive for CD45.2, indicating that they were initiated from thymocytes of the recipient mice." (PMID 26399548, 2015). "We also investigated the suppressive effect of IL-6 on more physiological immune responses of endogenous CD4+ T cells in protecting aged mice against the outgrowth of murine leukaemia virus (MuLV)-induced lymphoma, RMA21." (PMID 25850032, 2015). "Yield of isolated IEL was low or normal in all patients with OIE and AIE (0.1–0,3x106/6 duodenal biopsies) except for patient 11 with AIE complicated by a CD4+ lymphoma which infiltrated the gut epithelium." (PMID 26101883, 2015).
lymphoma (continued). "Blockade of the CD70 or CD80/86 pathways during co-culture with lymphoma cells reversed the differentiation of CD4+ cells into Tregs, and instead promoted the generation of anti-tumor Th17 cells." (PMID 25941795, 2015). "Tumors were subsequently classified by flow cytometry as either pre-B cell (IgM−), immature B cell (IgM+), mixed (IgM+/−) or as early hematopoietic progenitor-derived lymphomas (B220+CD4+)." (PMID 25857265, 2015). "In accordance with this finding, Toulza and colleagues have previously demonstrated that the concentration of CCL22 in adult T-cell leukemia/lymphoma patients was abnormally high and correlated with the frequency of CD4+FoxP3+ cells." (PMID 26020249, 2015). "We previously reported that HBZ transgenic (HBZ-Tg) mice which express HBZ in CD4+ T cells developed both systemic inflammation and T-lymphomas, indicating that they are suitable to evaluate the link, if any, between these phenomena." (PMID 26296091, 2015). "The resulting constructs were used to transfect MSB1; an MDV1-transformed CD4+ T-cell line derived from a spleen lymphoma induced by BC-1 strain of MDV1 and that constitutively expresses MDV1 miRNAs." (PMID 25503397, 2014). "MSB-1 derived from chicken Marek's disease (MD) lymphomas is an MDV-transformed CD4+ T-cell line for MD study." (PMID 25352859, 2014). "MSB-1 is an MDV-transformed CD4+ T-cell line derived from a spleen lymphoma induced by the BC-1 strain of MDV-1." (PMID 25352859, 2014). "RIM targeting of Bmi1 is largely a feature of B-cell lymphomas in the mouse, while Notch targeting predominates in the CD4+CD8+ lymphomas of Mmtv(d)-Myc mice." (PMID 24586197, 2014). "The mean CD4 count in patients with EBV-positive lymphoma (83.3 cells/μL) was significantly lower than that in patients with EBV-negative lymphoma (246.2 cells/μL; P < 0.01, Mann–Whitney test)." (PMID 24407967, 2014). "One secondary recipient from the mock group developed a CD4+ CD8+ mediastinal lymphoma that was CD45.2+ and therefore was derived from endogenous hematopoietic cells remaining in the recipient after irradiation." (PMID 23626802, 2013). "Based on these results, we determined that this lesion in the appendix was a lymphoma consisting of a diffuse infiltration of primary CD4- and TIA-1-positive cytotoxic T (Th1) cells." (PMID 23302373, 2013). "The patient had responded to cART with undetectable HIV-RNA and increased CD4 cell count one year prior to lymphoma presentation." (PMID 23880011, 2013). "The HIV staging at diagnosis of lymphoma showed that 14 (45.2%) had a CD4+ cell count below 200 cells/mm3." (PMID 24288620, 2013). "Although Tax-1 is able to efficiently transform rodent fibroblasts and to induce lymphoma in mouse model, it rarely transforms primary human CD4+ T lymphocytes." (PMID 24065965, 2013). "In blood, the mean percentages of PD-1+ CD4+ T cells were higher in cattle with lymphoma than in BLV+ and BLV- cattle." (PMID 23876077, 2013). "Full CD4+ T-cell recovery has been observed following autologous transplantation in HIV-1-infected patients with lymphoma." (PMID 24287598, 2013). "The resulting two independently derived transgenic mice expressed the transgene and developed a metastasic, angiogenic and transplantable CD4+CD8+CD69– lymphoma." (PMID 22558084, 2012). "One difference between MYC and MYC/FLIPL mice was that the ratio between immature CD4+/CD8+ and mature CD4+ T-cell lymphoma was skewed towards CD4+ lymphoma." (PMID 22393362, 2012). "NOD/SCID mice reconstituted with CD34+ HP/HSCs transduced with a lentivirus vector expressing the HTLV-1 oncoprotein Tax also developed CD4+ lymphomas." (PMID 23049525, 2012). "All these biomarkers were mainly produced by macrophages, and it was also reported that OPN is synthesized by macrophages as well as CD4+ T cells in HTLV-1-induced lymphoma." (PMID 22550534, 2012).
lymphoma (continued). "The majority of these animals were euthanized due to symptoms of simian AIDS with low CD4 count, and the lymphomas were diagnosed at necropsy." (PMID 23055934, 2012). "CD4+CD25highFOXP3+CD127low Tregs in the tumor microenvironment play an important role in lymphoma growth regulation." (PMID 22151904, 2011). "Intracellular cytometry showed the presence of Th17 cells, that is, CD4+ T cells coproducing IL-17 and IL-21, in eyes with lymphoma." (PMID 21949734, 2011). "Namely, after stimulation with epitope pulsed HLA matched lymphoma cells only a proportion (up to 70%) of CD69+ cells in an EBNA1 specific Th1 CD4+ T cell clone can be visualized by intracellular IFN-γ staining." (PMID 21429247, 2011). "Recent reports have shown that the presence of increased numbers of activated intra-tumoral CD4+ T cells predicts a better overall survival rate in patients with lymphoma." (PMID 22151904, 2011). "IL-2 is produced mainly by activated T helper CD4+ lymphocytes and is one of critical cytokines that control the proliferation and clonal expansion of transformed lymphoma cells." (PMID 20441582, 2010). "FIV-positive cats with lymphoma were reported to have substantially decreased CD4+ T cells, a reduced cell-mediated immunity and B-cell hyperactivity." (PMID 20167134, 2010). "Constitutively spliced transcript was almost undetectable at d0 in CD4+ T lymphocytes, but its levels gradually increased, peaking 22 days after infection, on the day of lymphoma onset." (PMID 20964812, 2010). "Nineteen patients with CD4+ HTLV-1+ acute or lymphoma ATLL were enrolled between October, 2002 and February, 2006 at 5 medical centers in the United States (see Checklist S1)." (PMID 19204798, 2009). "We also quantified CD4+ cells on 21 blood samples from patients with leukaemia or lymphoma by immunomagnetic isolation and counting on the pocH-100i and compared the results with those generated on the Epics XL flow cytometer." (PMID 18177434, 2009). "Intriguingly, since the introduction of ART, PCNS lymphoma has also been reported in individuals with CD4+ T cell counts over 200/μl or even over 500/μl." (PMID 17388662, 2007). "Here, the existence of a large cohort of HIV-infected individuals allowed us to study, in a controlled setting, predisease virus-specific CD4+ T cell function in rare individuals who developed PCNS lymphoma." (PMID 17388662, 2007). "Adult T-cell leukemia/lymphoma is a highly aggressive CD4+ T-cell malignancy that is refractory to conventional chemotherapeutic intervention." (PMID 17634129, 2007). "Half of the PCNS lymphoma patients fulfilled IR criteria (defined here as CD4+ T cell counts ≥500/μl blood)." (PMID 17388662, 2007). "EBV-specific CD4+ T cell-mediated IFN-γ production was assessed covering a range of 0.5–4.7 y prior to diagnosis of lymphoma." (PMID 17388662, 2007). "HTLV-1 is the etiologic agent of adult T-cell leukemia/lymphoma a highly aggressive CD4+ T-cell malignancy affecting approximately 1–5 % of HTLV-1-infected individuals after a latent period as long as three decades." (PMID 17634129, 2007). "We did detect, however, a slight under-representation of anti-HCV+ compared to anti-HCV− cases among NHL occurring at CD4+ counts below 50 cells μl−1 and among PBL, which are the two lymphoma subtypes where EBV is known to be most strongly implicated." (PMID 17106439, 2006). "The frequency of DP (CD4+8+) lymphomas was low compared to thefrequency of DP thymocytes in a normal AKR thymus." (PMID 1322753, 1992). "This assignment is supported by the fact that CD4-8+ lymphoma cell linesacquire CD4 expression after intrathymic (i.t.)transfer, a finding consistent with theestablished precursor potential of the normal immature CD4-8+ subset." (PMID 1840416, 1991). "MDV transforms CD4+ T cells into lymphoma cells, which highly express Meq." (PMID 41013577, 2025).